TLR5 (toll like receptor 5)
Diseases named in the same sentence as TLR5 in open-access papers (continued):
Sharing a sentence is not in itself a finding about the gene and the disease.
lupus (53 papers, 2004 to 2025). "In translational studies, whereby polymorphisms in the TLR5 and subsequent flagellin hyporesponsiveness are associated with improved health indicators in Crohn’s disease, CF and systemic lupus erythematosus." (PMID 22735858, 2012). "Moreover, differences in TLR5 activity have been implicated in several human diseases, including Crohn's disease, systemic lupus erythematosus, and Legionella pneumonia." (PMID 20953381, 2010). "For example, TLR2 is associated with systemic lupus erythematosus (SLE), sepsis, psoriasis; TLR3 with sepsis; TLR4 with SLE, sepsis, and psoriasis; TLR5 with psoriasis; TLR7 with SLE, stroke, and psoriasis; and TLR9 is involved in SLE, sepsis and psoriasis." (PMID 34203170, 2021). "Little is known about TLR5 in lupus but some contribution to SLE seems possible." (PMID 29650017, 2018). "For rheumatoid arthritis, systemic lupus erythematosus, ankylosing spondylitis and osteoarthritis diseases, those common factors include TNFSF10, CX3CR1, LY96, TLR5, TXN, TIA1, PRKCH, and PRF1." (PMID 26352601, 2015). "The TLR5 R392STOP polymorphism can reduce the immune response to flagellin; moreover, it may transfer resistance to a complex autoimmune disease, such as systemic lupus erythematosus (SLE)." (PMID 37998389, 2023).
influenza (48 papers, 2014 to 2025). An acute viral infection of the respiratory tract, occurring in isolated cases, in epidemics, or in pandemics; it is caused by serologically different strains of viruses (influenzaviruses) designated A, B, and C, has a 3-day incubation period, and usually lasts for 3 to 10 days. "Of note, TLR5-deficient mice, germ-free or antibiotic-treated animals had impaired responses to the influenza vaccine." (PMID 34451936, 2021). "The results presented in this human ex vivo model demonstrate novel insights into the effect of influenza on crucial S. pneumoniae-associated TLRs, and corroborates and provides mechanistic insights into the beneficial effects of TLR5 in mouse models." (PMID 34644311, 2021). "One study investigated the causal link between TLR5 and trivalent inactivated influenza vaccine (TIV)-induced humoral immune response in mice found that the microbiota had significant impacts on plasma B cell response to vaccination through TLR-5 sensing of bacterial flagellin." (PMID 36838417, 2023). "It is reported in those studies that conserved influenza epitopes linked to the flagellin either at the N or C terminus, or inclusive in its hypervariable region, did not impair the proper binding of the flagellin ligand to the TLR5." (PMID 31553755, 2019). "TLR5-mediated sensing of flagellin enhances the presence of short-lived plasma cells and immune response to influenza vaccine." (PMID 40083550, 2025). "The serum treated GF mice have revealed that TLR5 were sourced from commensals microflora, responsible to enhance the immune response against influenza vaccine." (PMID 39294611, 2024). "The literature has shown that knockouts (TLR5), germ-free mice vaccinated against influenza and treated with antibiotics, exhibited low levels of antigen-specific cells, and low IgG concentrations were observed 1 week after vaccination." (PMID 38414656, 2024). "TLR5-mediated sensing of flagellin produced by gut microbiota is critical to restoration of antibody response after influenza vaccination in germ-free or antibiotic-treated mice." (PMID 35891286, 2022). "Microbial flagellin is a ligand for TLR5 and stimulation of TLR5 boosted plasma cell numbers and antibody titers in response to the influenza vaccine." (PMID 34512600, 2021). "The magnitude of antibody response to the trivalent inactivated influenza vaccine in humans correlated with early TLR5 expression." (PMID 34512600, 2021). "TLR-5 agonists, such as flagellin, are potent and safe adjuvants for influenza vaccines administered via parenteral or mucosal routes in both animals and humans." (PMID 34868036, 2021). "In mice, it has been shown that bacterial flagellin stimulated TLR5-mediated sensing that was necessary for antibody production to the influenza vaccine." (PMID 34451936, 2021). "The addition of TLR5 ligand flagellin in influenza vaccines was shown to increase efficacy and improve the TLR5-mediated immune response." (PMID 33510644, 2020). "For example, the inclusion of flagellin, a TLR5 agonist, has been shown to increase the effectiveness of recombinant influenza vaccines." (PMID 32375274, 2020). "Accompaniment of flagellin with influenza vaccine or inactivated influenza viruses leads to higher IgA and IgG titers against influenza virus via TLR5." (PMID 33243230, 2020). "Accompaniment of flagellin with influenza vaccine or inactivated influenza viruses, can leads to higher IgA and IgG titers against influenza via TLR5." (PMID 33243230, 2020). "Flagellin intranasal administration specifically triggers TLR5-mediated transcription in the lungs from 2 to 30 h after a pneumococcus infection or from 7 to 14 days after an influenza infection." (PMID 31024555, 2019). "Toll-like receptor 5 (TLR-5) engagement at the mucosal surface of the gastrointestinal tract is known to enhance immune responses to influenza vaccination." (PMID 30820452, 2019).
influenza (continued). "In previous studies, the gut microbiome was determined to be a key modulator for metabolic disorders in TLR knockout mice, including TLR2 and TLR511, 17, and TLR5-mediated sensing of gut microbiota impacted antibody response to influenza vaccination." (PMID 27180604, 2016). "For example, the poor response to influenza vaccination observed in antibiotic-treated TLR5-/- mice can be ameliorated by oral reconstitution of flagellated E. coli." (PMID 27643883, 2016). "For example, in both germ-free and antibiotic-treated toll-like receptor 5 (TLR5)–/–mice vaccinated with the trivalent inactivated influenza vaccine, low antigen-specific plasma cell frequencies and IgG concentrations were observed at 1 week post vaccination." (PMID 28006021, 2016). "For example, the microbiota and their sensing via Toll-like receptor 5 (TLR5) were recently shown to be essential for productive antibody responses following influenza immunization in mice." (PMID 26187853, 2015). "However, when applied to influenza B vaccines, these formats showed limited efficacy due to weak activation of TLR5, resulting in poor immunogenicity." (PMID 41226335, 2025). "Furthermore, flagellin, a TLR5 agonist, can act as an adjuvant for influenza vaccination to promote the development of protective vaccine-induced immunity in the elderly, through increased seroconversion and antibody titers." (PMID 38482010, 2024). "Furthermore, TLR5 expression increased post-influenza vaccination in PBMCs from vaccinees and strongly correlated with vaccine-induced antibody responses." (PMID 38482010, 2024). "Flagellin could improve influenza vaccine immunogenicity via TLR5-mediated enhancement of short-lived plasma cell presence." (PMID 38473829, 2024). "TLR-5 mediated signals yield effective Abs response against influenza vaccine." (PMID 39294611, 2024). "A Phase III clinical trial shows that VAX125, a recombinant influenza vaccine consisting of flagellin (a TLR5 agonist), elicits vigorous responses against native virions at a relatively low dose of influenza hemagglutinin antigen, suggesting the substantial adjuvant effect of flagellin." (PMID 35986268, 2022). "Also, bacterial flagellin stimulation of Toll-like receptor 5 (TLR5) is needed to drive antibody production after influenza vaccination." (PMID 35417506, 2022). "Furthermore, sensing of host microbiota via TLR5 was found to facilitate antibody responses to influenza vaccines by promoting plasma cell differentiation." (PMID 33905460, 2021). "While TLR5 mediates the sensing of flagellin on bacteria, it has been shown that it is also necessary to generate B cell responses and Ab production to viral vaccines (e.g., inactivated influenza and inactivated polio vaccines)." (PMID 32670279, 2020). "Universal influenza vaccines have been reported previously, including self-assembling protein nanoparticles displaying M2e and Helix C with incorporation of TLR5 agonist flagellin, which has been shown to protect mice from lethal IAV challenge and also induced high levels of antibodies in chickens." (PMID 29381710, 2018). "However, our recent data indicated that the combination of local inoculation of flagellin (a TLR5 agonist) with antibiotic treatment can reduce the pulmonary pneumococcal burden after influenza." (PMID 27803187, 2016). "TLR5-mediated sensing of the gut microbiota is essential for effective antibody responses, as flagellin recognition through TLR5 promotes plasma cell differentiation and enhances humoral immunity to unadjuvanted vaccines, including the trivalent inactivated influenza vaccine (TIV)." (PMID 40444793, 2025). "One of the critical factors in VE is the expression of Toll-like receptor 5 (TLR5) within 3 days after vaccination, which correlates to the amount of hemagglutination inhibition (HAI) titers 4 weeks after influenza vaccination." (PMID 36313997, 2022).
influenza (continued). "Similar data were obtained in models of non-antibiotic-driven dysbiosis; for instance, TLR5 double-knock-out mice showed a reduction in both antibody titers and specific plasma cell differentiation after the influenza vaccine." (PMID 37897011, 2023). "As an example, by using a systems vaccinology approach to assess immune responses stimulated by trivalent inactivated influenza vaccination (TIV), the gene expression of TLR5 at day 3 after vaccination was found to correlate with influenza vaccination response (HAI titers) 28 days after vaccination." (PMID 32670279, 2020). "Toll-like receptor 5 (TLR5) was identified as the potential molecular link between ABX and defective humoral immunity since abrogation of TLR5-mediated sensing of flagellin impaired plasma cell and antibody responses to inactivated influenza vaccination in mice." (PMID 41282134, 2025).
Obesity (31 papers, 2011 to 2025). Accumulation of substantial excess body fat. "Elevated TLR5 expression in adipose tissue is associated with obesity and metabolic dysfunctions in humans." (PMID 40444793, 2025). "In humans, a nonsense polymorphism (R392X) in the TLR5 gene has been associated with protection against obesity while predisposing carriers to diabetes." (PMID 40558558, 2025). "TLR5 modulates susceptibility to obesity and alters metabolism through gut microbiota; however, little is known about the role TLR5 plays in autoimmunity, especially in T1D." (PMID 38482010, 2024). "In an animal study, a deficiency in flagellin-recognizing TLR5 was associated with obesity development and insulin resistance along with an obese-type gut microbiota." (PMID 31635264, 2019). "Since genetic variants of TLR5 have been clinically associated with disease outcomes such as obesity, type 2 diabetes, and colorectal cancer, it is important to determine the functional role of alternative splicing variants of TLR5." (PMID 28948171, 2017). "In contrast to the ob/ob mouse model of obesity, which is characterized by a phylum-level shift in Bacteroidetes and Firmicutes, the TLR5-deficient mice exhibit altered abundance in over one-hundred specific bacterial phylotypes." (PMID 22115311, 2011). "In addition, TLR5 gene knockout has been shown to impair some of the beneficial effects of weight loss in diet-induced obesity models." (PMID 40558558, 2025). "However, this protective effect against obesity is counterbalanced by the increased risk of type 2 diabetes mellitus, highlighting the complex relationship between TLR5 function and metabolic regulation." (PMID 40444793, 2025). "A host–microbiota interaction implicated in inflammation and obesity is the sensing of flagella through TLR5, which controls motile bacteria by different mechanisms, including the production of antimicrobial peptides and anti-flagella immunoglobulins that regulate the microbiota in the gut." (PMID 34066026, 2021). "It was described that TLR2, TLR4, or TLR5 deficiency have a major role on obesity development." (PMID 26635627, 2015). "Along with human studies connecting altered gut microbiota to obesity, it has been previously reported that deficiencies in innate immune factors, such as toll-like receptor-5 (TLR-5), have been associated with significant alterations in gut microbiota and adiposity." (PMID 25517731, 2014). "A direct causal relationship between the altered gut microbiota and obesity was demonstrated by gut microbiota transplants where GF mice receiving the gut microbiota from TLR-5-deficient mice gained significantly more weight compared to mice that received gut microbiota from wild-type mice." (PMID 22115311, 2011). "However, the Toll-like receptor-5-deficient (Tlr5 KO) mouse group, also on a high-fat diet, displayed significantly lower serum levels of IL-6 than the other groups, suggesting that obesity increases the expression of proinflammatory factors, thereby aggravating OA progression." (PMID 38052778, 2023). "Supporting the involvement of TLR5 pathways, Clostridium cluster XIV bacteria have been implicated in the development of obesity via TLR5 signaling." (PMID 40558558, 2025). "This is relevant as flagellins are canonical effectors of Toll-like receptor 5 and have been suggested to contribute to obesity." (PMID 35599315, 2022). "In the presented study, we analyzed three SNPs located in TLR5 due to the reported relevance of TLR5 SNPs in colorectal cancer, obesity, and diabetes." (PMID 36140341, 2022). "Animals lacking TLR4 are relatively protected from HFD induced obesity and diabetes, whereas animals lacking TLR5, on the other hand, have an increased risk of obesity." (PMID 38140398, 2023). "It was recently found that TLR5 signaling in adipose tissue could corroborate to obesity, inflammation and metabolic alterations." (PMID 26635627, 2015).
Obesity (continued). "This decrease in functional efficacy could be physiologically important for growth performance, for example, a mouse knock out of a toll-like receptor (TLR5) has previously been shown to modulate gut microbiome characteristic of obesity and other metabolic disorders." (PMID 31952471, 2020). "The magnitudes of the obesity-induced upregulation of the TLR1, TLR4, TLR5, TLR8, TLR9, and TLR12 genes in the visceral adipose tissue were even greater in the diet-induced obesity (DIO) mice than in the ob/ob mice." (PMID 26681840, 2015). "Our results add NOD2 as an important PRR to the growing list of immune components that protect against dysbiosis and metabolic disease during obesity, which includes TLR2, TLR5, and inflammasome components." (PMID 25666722, 2015). "Transplantation of TLR5−/− microbiota into wild type germ-free mice conferred many aspects of the TLR5−/− phenotype to the wild type germ-free hosts, including hyperphagia, obesity, hyperglycemia, insulin resistance, and elevated levels of proinflammatory cytokines." (PMID 26681840, 2015). "Although food restriction prevents obesity, but not insulin resistance, in TLR5-deficient mice, limited information is known regarding the LFD effect on TLR5-deficient obese mice." (PMID 26681840, 2015). "Similarly, mouse models without TLR5 expression were used to present obesity, hepatic steatosis and insulin resistance, the main characteristics of our study cohort." (PMID 35806447, 2022). "Although adaptive immunity is not directly related to the process of obesity in TLR5−/− mice, it should be noted that the development of adiposity could be controlled by balancing the complex microbiota." (PMID 22383967, 2012). "In addition, the role played by TLR5 in obesity is not well-established." (PMID 26635627, 2015).
breast carcinoma (28 papers, 2012 to 2025). "On the other hand, overexpression of TLR5 in breast tumors has been linked to increased metastasis and TLR5 polymorphisms have been linked to breast cancer susceptibility." (PMID 35805158, 2022). "Another question is the molecular mechanism underlying regulation of TLR5 in different histological subtype of breast cancer." (PMID 31576678, 2019). "In sum, to the best of our knowledge, this study is the first to suggest a link between TLR5 SNPs and breast cancer susceptibility in humans." (PMID 29179462, 2017). "Our findings thus indicate that TLR5 SNP rs5744168 is associated with sporadic breast cancer occurrence." (PMID 29179462, 2017). "The association between the level of TLR5 expression and the clinical features of breast cancer patients were analyzed." (PMID 29179462, 2017). "In a case-control study, we also analyzed associations between TLR5 single nucleotide polymorphisms (SNPs) and breast cancer risk." (PMID 29179462, 2017). "The nonsense SNP rs5744168 causes truncation of the TLR5 transmembrane signaling domain and was associated with breast cancer risk (p<0.05)." (PMID 29179462, 2017). "Our aim in the present study, therefore, was to clarify the relation between TLR5 coding SNPs and susceptibility to breast cancer in Asian populations." (PMID 29179462, 2017). "In this study, we further investigated the underlying antitumor mechanisms of TLR5 signaling in breast cancer cells by examining the function of MAP1S." (PMID 24466264, 2014). "The TLR5 SNP rs5744168 was linked to the incidence of sporadic breast cancer." (PMID 39475915, 2024). "The activation of TLR5 on dendritic cells can promote the presentation of tumor-associated antigens to T cells, enhancing anti-tumor immunity and overcoming resistance to immune checkpoint therapy in a syngeneic breast cancer model." (PMID 38903515, 2024). "Indeed, in breast cancer, deficiency in TLR5 activity is associated with an increased cancer progression while, on the other hand, TLR5 upregulation in ovarian cancer has a negative effect on long-term survival." (PMID 34884547, 2021). "Collectively, these results indicated that MAP1S is associated with breast cancer TLR5 pathway." (PMID 24466264, 2014). "Furthermore, TLR5 expression and activation may interact with other signaling pathways implicated in breast cancer, such as the NF-κB pathway, further influencing tumor behavior." (PMID 38903515, 2024). "Furthermore, TLR5 overexpression has been associated with lymph node metastasis and cancer grade in breast carcinomas, and TLR5 SNP rs5744168 has been found to be associated with sporadic breast cancer occurrence." (PMID 38903515, 2024). "Among them, TLR5 is expressed in breast cancer cells and exerts antitumor effects via the MyD88-dependent NF-κB signaling pathway." (PMID 40497049, 2025). "The TCGA data show that TLR5 high expressed indicates a favorable prognosis in breast cancer patients." (PMID 38903515, 2024). "We are among the first research groups to demonstrate that certain TLRs, such as TLR5, are functional not only in traditional innate immune cells like macrophages and dendritic cells but also in breast cancer epithelial cells." (PMID 38903515, 2024). "We found that TLR5 is highly expressed in breast carcinomas and is overly responsive in breast cancer cells." (PMID 38903515, 2024). "In cancer, TLR5 has been shown to be highly expressed in patients with gastric carcinoma and breast cancer." (PMID 37112730, 2023). "TLR5 agonists in combination with immune checkpoint therapies (ICT) enhance survival in ICT-refractory murine 4T1 mammary carcinoma and B16-F10 melanoma tumors." (PMID 36635337, 2023). "In the breast cancer, TLR5 activation leads to autophagy via the MAP1S autophagy protein which induces IL-8 and TNF-α in the MCF-7 cell line." (PMID 36539522, 2022).